PAFAH1B3 (platelet activating factor acetylhydrolase 1b catalytic subunit 3)
Diseases named in the same sentence as PAFAH1B3 in open-access papers (continued):
Sharing a sentence is not in itself a finding about the gene and the disease.
cancer (continued). "Firstly, we demonstrated that PAFAH1B3 was highly expressed in a wide variety of malignant tumors compared with normal samples." (PMID 34490100, 2021). "A loss of function assay was performed to examine the functional role of PAFAH1B3 in LIHC cancer cells." (PMID 35187070, 2021). "PAFAH1B3 was primarily involved in cell proliferation and oxidative phosphorylation signaling pathways in various cancers." (PMID 35187070, 2021). "Next, we examined the expression level of PAFAH1B3 and its prognostic value using pan-cancer TCGA and GTEx data obtained from the UCSC Xena database." (PMID 33732641, 2021). "Findings indicate that PAFAH1B3 expression is significantly correlated with immune cell infiltration during human cancer." (PMID 35187070, 2021). "We used the ONCOMINE, TIMER and HCCDB cancer database to analyze the mRNA expression of PAFAH1B3 in multiple cancer types." (PMID 34490100, 2021). "We evaluated the prognostic value of PAFAH1B3 in a variety of malignant tumors using the GEPIA database." (PMID 34490100, 2021). "In this study, PAFAH1B3 was elevated in human pan-cancer, and this correlated with greater pathology and poor prognosis, in particular for non-small cell lung cancer (NSCLC) and liver hepatocellular carcinoma (LIHC)." (PMID 35187070, 2021). "This study provides the first evidence that PAFAH1B3 impacts cancer progression and immune responses to human pan-cancer." (PMID 35187070, 2021). "PAFAH1B3 expression was analyzed in The Cancer Genome Atlas (TCGA) and genotype-tissue expression pan-cancer data." (PMID 33732641, 2021). "Platelet activating factor acetylhydrolase 1B3 (PAFAH1B3), a cancer-relevant molecular, was found to play a vital role in tumorigenesis and aggressiveness in several cancer types." (PMID 34136395, 2021). "Trans-well and invasion assays showed that cancer cell migration and invasion were dramatically repressed in PAFAH1B3 knockdown cells compared with the control group." (PMID 35187070, 2021). "Recent studies showed PAFAH1B3 as a key metabolic driver was correlated with poor prognosis, and PAFAH1B3 knockdown or pharmacological inhibition impaired cancer cell survival through enhancing tumor-suppressing signaling lipids." (PMID 34490100, 2021). "Given that some cancers lack normal tissue data in TCGA databases, PAFAH1B3 expression was also assessed in pan-cancers using the TCGA/GTEx databases." (PMID 35187070, 2021). "In this study, public databases were used for the first time to show that PAFAH1B3 is highly expressed in diverse cancer types." (PMID 35187070, 2021). "Emerging evidence shows that PAFAH1B3 plays an important role in apoptosis, cancer metastasis, and angiogenesis during cancer." (PMID 35187070, 2021). "High expression of PAFAH1B3 was also associated with TMB, MSI, immune cell infiltration, and sensitivity to multiple cancer drugs." (PMID 35187070, 2021). "Nevertheless, the expression pattern of PAFAH1B3 in various human cancers and its prognostic values are still elusive." (PMID 33732641, 2021). "Metabolomics analysis revealed that PAFAH1B3 promotes tumor invasion by regulating the precancer signaling lipid metabolism network; thus, targeting PAFAH1B3 was shown to upregulate the pathogenicity of tumor suppressor lipids to attenuate cancer." (PMID 34490100, 2021). "The correlation between PAFAH1B3 expression and development of different immune and molecular subtypes in pan-cancer was assessed using the TISIDB database." (PMID 35187070, 2021). "In summary, PAFAH1B3 is a potential biomarker for diagnosis and prognosis in different cancer types and a promising molecular target for LIHC." (PMID 35187070, 2021).
cancer (continued). "Pharmacological blockade of PAFAH1B2 and PAFAH1B3 impaired cancer pathogenicity across a number of different types of cancer cells, including prostate cancer." (PMID 30197761, 2018). "This study silenced the mRNA of PAFAH1B3 to investigate its role in cancer." (PMID 41009369, 2025). "Many studies have found that PAFAH1B3 plays an important role in various cancers." (PMID 35534807, 2022). "P11, an inhibitor of PAFAH1B2 and PAFAH1B3, can impair the pathogenicity of these cancers." (PMID 35534807, 2022). "Our results showed that PAFAH1B3 can be used as a pan-cancer marker for tumor prognosis." (PMID 34490100, 2021). "Results showed that PAFAH1B3 has different expression patterns in pan-cancer." (PMID 35187070, 2021). "The results showed that higher PAFAH1B3 expression was significantly associated with poor prognosis in ACC (P = 0.00023), LIHC (P = 0.0011), LUAD (P = 0.015), MESO (P = 0.003), SARC (P = 0.011), and SKCM (P = 0.0033), indicating that PAFAH1B3 is a potential oncogene in these types of cancers." (PMID 33732641, 2021). "However, the specific role of PAFAH1B3 in diagnosis, prognosis, and immune regulation in various types of cancer remains unexplored." (PMID 35187070, 2021). "Moreover, these two studies revealed that PAFAH1B3 knockdown significantly impaired cell migration and invasion potential, suggesting the pivotal role of PAFAH1B3 in keeping the aggressive property of cancer." (PMID 34136395, 2021). "In our study, we used multiple cancer databases to analyze the PAFAH1B3 expression in various cancer, and further analyzed the prognostic value, co-expression genes, regulator networks of PAFAH1B3 in HCC." (PMID 34490100, 2021). "By modulating tumor-suppressing lipids, PAFAH1B3 promotes cancer cell aggressiveness." (PMID 35187070, 2021). "Several studies have indicated the relationship between PAFAH1B3 and cancer progression." (PMID 34490100, 2021). "Since previous results have shown that PAFAH1B3 expression correlates with prognosis for a wide range of cancers, this study assessed whether PAFAH1B3 may act as a detection index for cancer diagnosis." (PMID 35187070, 2021). "Overall, these results showed that PAFAH1B3 was upregulated in many human cancer types." (PMID 35187070, 2021). "PAFAH1B3 was uniquely expressed in different molecular subtypes of cancer." (PMID 35187070, 2021). "Selective inhibition of PAFAH1B3 has been reported to impair cancer cell survival." (PMID 33732641, 2021). "In addition, Cancer Cell Line Encyclopedia (CCLE) databases analysis showed that PAFAH1B3 was overexpressed in many cancer cell lines." (PMID 35187070, 2021). "TIMER results showed that PAFAH1B3 expression correlated with CD8+ T cell abundance in 27 cancers, CD4+ T cell abundance in 28 cancers, neutrophil abundance in 30 cancers, dendritic cell (DC) abundance in 30 cancers, macrophage abundance in 27 cancers, and B cell abundance in 29 cancers." (PMID 35187070, 2021). "Results indicate that PAFAH1B3 may serve as a biomarker for the clinical detection of cancer." (PMID 35187070, 2021). "In addition, the pharmacological inhibition or RNA interference-mediated inactivation of PAFAH1B3 could impair cancer cell survival, migration and invasiveness in vitro and slow tumor growth in vivo." (PMID 34136395, 2021). "In addition, PAFAH1B3 expression was positively associated with tumor mutational burden (TMB), microsatellite instability (MSI), immune cell infiltration, immune-modulatory related gene expression, and diverse cancer drug sensitivity in human cancer." (PMID 35187070, 2021).
cancer (continued). "Platelet-activating factor acetylhydrolase 1B3 (PAFAH1B3), a catalytic subunit of PAFAH, is important for apoptosis, metastasis, and angiogenesis in cancer." (PMID 41009369, 2025). "Compared with that in paracancerous pancreatic tissues, PAFAH1B3 was highly expressed in PDAC tissues, and the level of expression increased with the increasing of cancer grade." (PMID 38649699, 2024). "Platelet-activating factor acetylhydrolase 1B3 (PAFAH1B3), one of the catalytic subunits of PAFAH, is essential for the growth, metastasis, angiogenesis, and development of drug resistance in cancer." (PMID 38063949, 2023). "PAFAH1B3 expression was correlated with distant metastasis of LUAD, and one characteristic of cancer metastasis is invasion." (PMID 35534807, 2022). "Platelet-activating factor acetylhydrolase 1B3 (PAFAH1B3) plays a critical role in cancer initiation, metastasis, and progression; however, it remains unknown how PAFAH1B3 impacts cancer diagnosis and prognosis or regulates the immune response to different types of cancer." (PMID 35187070, 2021). "Platelet-activating factor acetylhydrolase 1B3 (PAFAH1B3), one of the catalytic subunits of PAFAH, plays an important role in apoptosis, cancer metastasis, and angiogenesis during cancer." (PMID 35187070, 2021). "PAFAH1B3 is involved in diverse cancer-related signaling pathways, including PAF and WNT, and facilitates cancer progression." (PMID 35187070, 2021). "Platelet activating factor acetylhydrolase 1b catalytic subunit 3 (PAFAH1B3) is one of the catalytic subunits of Platelet-activating factor (PAF) acetylhydrolase, which was reported to play crucial roles in certain types of cancers by regulating PAF activity." (PMID 33732641, 2021). "In cancer tissues, KLF9 expression was low, and PAFAH1B3 expression was high." (PMID 38649699, 2024). "PAFAH1B3, as one of the top 50 overexpressed metabolic enzymes in human cancers, is involved in multiple types of tumors, but the roles of PAFAH1B3 in LUAD have not been clarified." (PMID 35534807, 2022). "The correlation between PAFAH1B3 expression and sensitivity to different drugs was assessed using cancer cell lines from the Genomics of Drug Sensitivity in Cancer (GDSC) database and the Cancer Therapeutics Response Portal (CTRP) database." (PMID 35187070, 2021). "In summary, this study elucidates the clinical significance and biological function of PAFAH1B3 during liver hepatocellular carcinoma (LIHC) and may serve as a potential biomarker for the diagnosis and prognosis of various cancer types." (PMID 35187070, 2021). "Other proteins included in this component related to cancer are NUMA1, SERPINA1, and PAFAH1B3." (PMID 32525929, 2020). "In this study, PAFAH1B3 expression was significantly correlated with CD8+ T cell abundance in 27 cancers, CD4+ T cell abundance in 28 cancers, neutrophil abundance in 30 cancers, DC abundance in 30 cancers, macrophage abundance in 27 cancers, and B cell abundance in 29 cancers." (PMID 35187070, 2021). "However, no studies have analyzed the clinical significance of PAFAH1B3 in pan-cancer." (PMID 35187070, 2021). "However, a recent study demonstrated that PAFAH1B3 knockdown did not change PAF levels or PAFAH hydrolytic activity, indicating that the impact of PAFAH1B3-mediated cancer pathogenicity may not depend on PAF signaling pathways." (PMID 34136395, 2021).
tumor (17 papers, 2020 to 2025). "In this study, we found that PAFAH1B3 is not only linked with TEX infiltration but also involved in the regulation of HCC progression as a tumor stemness-related gene." (PMID 37957420, 2023). "Univariate and multivariate Cox regression analyses showed that TM stage, pathologic stage, tumor status, and PAFAH1B3 expression were significantly associated with OS." (PMID 35187070, 2021). "Univariate and multivariate Cox regression analyses showed that TM stage, pathologic stage, tumor status, and PAFAH1B3 expression were significantly associated with the OS." (PMID 35187070, 2021). "On the other hand, the signaling mechanisms underlying the function of PAFAH1B3 in tumor cells are largely unknown to date." (PMID 33732641, 2021). "Finally, we attempted to find an association between PAFAH1B3 and tumor immune infiltration." (PMID 35534807, 2022). "Following intratumoral administration of cholesterol-conjugated si-PAFAH1B3, a significant reduction in tumor growth and tumor weight was observed compared to the PBS and NC groups." (PMID 41009369, 2025). "A xenograft tumor model was established to explore the function of PAFAH1B3 in vivo, and EMT-related markers were detected using RT-PCR and IHC analyses." (PMID 41009369, 2025). "To assess the potential of si-PAFAH1B3 as a therapeutic target, we developed xenograft tumor models by subcutaneously injecting SMMC-7721 cells into nude mice." (PMID 41009369, 2025). "There were more intrahepatic metastases in the PAFAH1B3-Flag group than in the NC group, and HE staining confirmed that the tumour was an intrahepatic metastasis." (PMID 38649699, 2024). "In our study, the exosomal protein PAFAH1B3 was served to augment the motility of cells within the tumor cell mass that exhibit low expression of PAFAH1B3." (PMID 39553628, 2024). "Recent studies have shown that PAFAH1B3 also plays an important regulatory role in the occurrence and development of tumours." (PMID 38649699, 2024). "The results showed that the weight, volume and Ki-67 expression level of the tumours formed by SW1990 cells transduced with lentivirus containing PAFAH1B3-Flag in nude mice were significantly greater than those in the NC group." (PMID 38649699, 2024). "The results showed that the expression of PAFAH1B3 was significantly correlated with tumour size, lymph node metastasis status and TNM stage in PDAC patients." (PMID 38649699, 2024). "In conclusion, PAFAH1B3 is closely related to TEX in the tumor microenvironment (TME) and can be a useful indicator for PD1/PD-L1 therapy." (PMID 38063949, 2023). "The expression of PAFAH1B3 was increased in HCC tumor tissue, and the effectiveness of treatment is enhanced by PAFAH1B3 blockade, which reduces the proliferation of HCC tumor cells." (PMID 38063949, 2023). "As shown in the tumor growth curve, the growth rate of tumors was significantly slowed in the group with reduced PAFAH1B3 expression compared with the shControl group (P < 0.05)." (PMID 35534807, 2022). "We also proved that PAFAH1B3 downregulation inhibited tumorigenesis and neutrophil infiltration in the xenograft tumor model." (PMID 35534807, 2022). "More studies are needed to further study the changes in downstream signaling pathways and tumor signaling lipids that occur after silencing PAFAH1B3." (PMID 35534807, 2022). "Through a xenograft tumor model, we proved that knockdown of PAFAH1B3 inhibited the tumorigenesis of LUAD cells." (PMID 35534807, 2022). "Then the xenograft tumor tissues were used for IHC analyses to assess the changes in EMT-related markers after PAFAH1B3 knockdown." (PMID 35534807, 2022). "siRNA transfections and inhibitor of PAFAH1B3 P11 were used to verify the anti-tumor effect on HCC cell lines." (PMID 34490100, 2021). "For example, PAFAH1B3 expression was found to be higher in hypopharyngeal squamous cell carcinoma tissues than in adjacent non-tumor samples and predicted a poor outcome." (PMID 33732641, 2021).
tumor (continued). "Overexpressed PAFAH1B3 in NSCLC was strongly associated with pathologic stage, TNM stage, residual tumor, and outcome of primary therapy." (PMID 35187070, 2021). "The expression of PAFAH1B3 in tumor tissues and the adjacent normal tissues, according to t-test in HCCDB." (PMID 34490100, 2021). "High PAFAH1B3 expression was significantly associated with histologic stage, tumor status, pathologic stage, TNM stage, residual tumor, vascular invasion, race, BMI, gender, age, weight, and height." (PMID 35187070, 2021). "TNM stages, tumor status, histologic stage, and PAFAH1B3 expression were also included in a nomogram to predict OS, DSS, and PFI during LIHC." (PMID 35187070, 2021). "In this study, we found that high PAFAH1B3 expression was significantly associated with histologic stage, tumor status, pathologic stage, TNM stage, residual tumor, vascular invasion, race, BMI, gender, age, weight, and height in LIHC." (PMID 35187070, 2021). "The results manifested that knockdown of PAFAH1B3 distinctly decreased the tumor volume and the tumor weight." (PMID 34136395, 2021). "High PAFAH1B3 expression was significantly associated with pathologic stage, TNM stage, residual tumor, and primary therapy outcome." (PMID 35187070, 2021). "To investigate whether si-PAFAH1B3 could be a promising therapeutic target, we constructed xenograft tumor models of nude mice subcutaneously injecting them with SMMC-7721 cells." (PMID 41009369, 2025). "Furthermore, intratumoral injection of PAFAH1B3 inhibitor suppressed tumor growth, and PAFAH1B3 knockdown increased and decreased the levels of the E-cadherin and N-cadherin, respectively." (PMID 41009369, 2025). "Consequently, PAFAH1B3 has the potential to act as a therapeutic target for intervention in the incipient phases of tumor metastasis." (PMID 39553628, 2024). "Correlation analysis of the pathological features and prognosis of PDAC patients revealed that high expression of PAFAH1B3 was significantly correlated with lymph node metastasis, large tumour size and advanced TNM stage and was a poor prognostic factor in PDAC patients." (PMID 38649699, 2024). "In addition, PAFAH1B3 protein was visibly elevated in HCC tumor tissue by IHC analysis, which is consistent with the previous report." (PMID 37957420, 2023). "To explore whether knockdown of PAFAH1B3 reduced neutrophil infiltration, we assessed the protein expression of neutrophil surface antigen Ly6g in xenograft tumor tissues by IHC." (PMID 35534807, 2022). "Furthermore, our results showed that the PAFAH1B3-high expression group had significantly enriched tumor-promoting cells, such as nTregs, exhausted T cells and neutrophils." (PMID 35534807, 2022). "The xenograft tumor model was constructed to explore the function of PAFAH1B3 in vivo." (PMID 35534807, 2022). "Here, by data mining using TCGA datasets, the hyperexpression of PAFAH1B3 was observed in 24 types of tumor tissues compared with normal tissues, suggesting that PAFAH1B3 might serve as a novel oncogene in these tumor types." (PMID 33732641, 2021). "PAFAH1B3 plays an important role on occurrence and development in a variety tumor." (PMID 34490100, 2021). "Finally, to further explore the potential relationship between PAFAH1B3 and tumor metabolic activity, we tested the expression of key targets involved in lipid and glucose metabolism." (PMID 34490100, 2021). "Importantly, further investigation in vitro revealed the correlation of PAFAH1B3 with proliferation, apoptosis, cell cycle, metastasis, and tumor-infiltrating immune cells." (PMID 34490100, 2021). "Moreover, positive correlations were detected between PAFAH1B3 expression and infiltration levels of CD8-positive T cells and M1 macrophages, indicating a key role of PAFAH1B3 in regulating tumor immunology." (PMID 33732641, 2021). "Whether targeting PAFAH1B3 can affect the anti-tumor immune response remains to be verified." (PMID 34490100, 2021).